CD4 (CD4 molecule)
Diseases named in the same sentence as CD4 in open-access papers (continued):
Sharing a sentence is not in itself a finding about the gene and the disease.
anemia (continued). "Out of the total 25 potential risk score points, non-HIV related factors (tachycardia, chief complaint of fever, anemia and hyponatremia) contributed a similar amount of weight compared to HIV-related factors (CD4 count and HAART use)." (PMID 23940557, 2013). "Vitamin D deficiency was noted to be more prevalent in patients with hypoalbuminemia (97.4%), anemia (86.1%), HIV co-infected patients with CD4 count <200cells/mm3 (83.2%) and hypocalcemia corrected for serum albumin levels (67%)." (PMID 23886009, 2013). "In both ARV groups, majority were heterosexuals (92.8%), males (52.9%), and ever married (56.5%), and most were admitted with anaemia-PCV < 30% (60%) and severe immunosuppression CD4 ≤ 200 cells/ul (76.2%)." (PMID 23019521, 2012). "Anemia within three years prior to HAART (p = 0.07), and CD4+ = 51-200 cells/mm3 (p = 0.06) were of borderline significance." (PMID 22339893, 2012). "In multivariable analysis, after adjusting for baseline age, cohort, CD4+ cell count, WHO stage, anaemia, weight, viral load, and calendar year of initiation, men were more likely to be truly LTF than women (AHR 1.20, 95% CI 1.12–1.28)." (PMID 22973181, 2012). "Several studies from Europe and North America have shown that anemia is an independent predictor of mortality in patients on ART, even after controlling for CD4 cell count and viral load." (PMID 18430196, 2008). "Bedridden and ambulatory functional status, poor ART adherence, CD4 count below the threshold (<200 cells/mm3), advanced WHO clinical staging, missing of cotrimoxazole and isoniazid preventing therapy, anemia, and extra pulmonary TB were significant predictors of mortality." (PMID 39509354, 2024). "Being bedridden and ambulatory functional status, poor ART adherence, CD4 count below the threshold (<200 cells/mm3), advanced WHO clinical staging, missing of cotrimoxazole and isoniazid preventing therapy, anemia and extra pulmonary TB were significant predictors of mortality." (PMID 39509354, 2024). "Blood tests showed anemia, elevated D-dimer, and HIV-1 positivity with a low CD4 count." (PMID 39022523, 2024). "Anemia is independent of CD4+, T-lymphocyte count, and plasma HIV RNA concentration in the interaction between anemia and decreased survival." (PMID 38903363, 2024). "Being bedridden and ambulatory functional status, poor ART adherence, CD4 count below the threshold (<200 cells/mm3), advanced WHO clinical staging, not provision of cotrimoxazole and isoniazid preventing therapy, anemia and extra pulmonary TB were significant predictors of mortality." (PMID 39509354, 2024). "Currently, the less severe ANI and MND are observed even among patients with high CD4+ count and undetectable viral load as opposed to pre- ART era, where low CD4+ count, low weight, and anemia were the significant risks for HAND." (PMID 37228133, 2023). "A large retrospective Brazilian cohort study found anemia in 56% of pregnant women with WLH, which was associated with low CD4+ cell count and did not have any association with ART." (PMID 36870111, 2023). "Even though antiretroviral therapy (ART) access for human immunodeficiency virus (HIV)-infected children increased dramatically, anaemia has continued as a challenge regardless of a cluster of differentiation (CD4) count and viral load." (PMID 37706072, 2023). "When we combine our results on relationships between Hb values and surrogates of HIV (CD4 count and HIV viral load) or of TB (dissemination score), we can argue that anemia in this study population is likely more noticeably related to progression of TB progression than that driven by HIV." (PMID 37143662, 2023). "There is significant difference in anemia in MHC and OH infected with different CD4 group (P<0.01)." (PMID 35245289, 2022). "Correlates which may contribute to lower levels of physical activity and capacity in HIV-infected were HIV status (CD4 count), chronic inflammation, HIV related wasting and anaemia." (PMID 35061774, 2022).
anemia (continued). "Anemia prevalence differs in MHC and OH infected in patients with CD4 count ≤200 (P≤0.03)." (PMID 35245289, 2022). "In a systematic review and meta-analysis conducted in low and middle income countries, independent factors associated with early mortality in 30 studies included low baseline CD4 cell count, male sex, advanced WHO clinical stage, low body mass index, anemia, and age greater than 40 years." (PMID 35668350, 2022). "Similarly, most people with severe anaemia had low CD4 T-cell counts (83.3%) and CD4:CD8 ratio (79.2%) than those with moderate (67.3% and 43.6%) and mild anaemia (40.0% and 22.4%), respectively, P < 0.001." (PMID 35022106, 2022). "In patients with CD4 count ≤200cells/μl anemia were 10.8% that was not similar with 20% from Southwestern Ethiopia." (PMID 35245289, 2022). "Even though antiretroviral therapy access for HIV infected children increased dramatically, anemia have been continued as a challenge regardless of a cluster of differentiation (CD4) count and viral load." (PMID 33785009, 2021). "The artificial MRSA infection through the acute injury promotes the changing of blood profile such as total erythrocytes, leukocytes, neutrophils, lymphocytes, total plasma protein, CRP, the subset of circulatory CD4+, CD8+, and COX-2 and leads to anemia macrocytic normochromic." (PMID 34566324, 2021). "In this case, the patient manifested unusual clinical presentations (fatigue, splenomegaly, anemia, no fever, hemorrhages, or concurrent infections), which frequently occur in individuals with low CD4+ T-cell counts (23.01%)." (PMID 34976855, 2021). "The risk of anemia is present in children living with HIV infection but the risk for anemia is increased based on (WHO clinical staging III and IV, CD4 count below the threshold level, CPT non-users, and poor level of adherence)." (PMID 33785009, 2021). "Factors associated with fatigue included: Parity, CD4 count 200–499 cells/mm3, Clinical Stage II or IV HIV, anemia, co-morbidities, depression, and not being physically active." (PMID 32295546, 2020). "In addition, anaemia was more common in females, while elevated levels of CRP, creatinine and creatine kinase and decreased levels of platelets and CD4+ cells were more common in males." (PMID 33009426, 2020). "It should be noted that severe/moderate anaemia was also present in around one-quarter of patients with normal nutritional status, or with CD4+ count > 200 cells/mm3, or with better WHO clinical stage, and around one in five patients with VL<1.000 copies/mL." (PMID 33170905, 2020). "In this model, women with advanced maternal age (≥35 years) have an adjusted odds ratio of having an adverse pregnancy outcome that is 0.6 (95% CI.1 to 2.4; P = .50) times that of women aged <35 years, after controlling for IPT use, CD4 count, PMTCT regimen, viral load, BMI, and anemia." (PMID 31631221, 2020). "Independent of viral load and CD4 counts, the incidence of anaemia can influence the progression of HIV to AIDS whilst the recovery from anaemia significantly reduces the risk of death and improves the survival of those infected with HIV." (PMID 33425126, 2020). "In adjusted logistic regression analysis, IPT-unexposed women had 2.5 (95% confidence interval [CI], 1.0 to 6.5; P = .048) times the odds of having an adverse pregnancy outcome compared with IPT-exposed women after controlling for CD4 count, PMTCT regimen, viral load, maternal age, BMI, and anemia." (PMID 31631221, 2020). "By depleting the CD4+ T cells, HIV influences the rate of maternal anaemia progression." (PMID 33228585, 2020). "The present study confirmed these findings, however we report much larger increased risks of anemia (HR = 8.40, 95%CI: 6.85, 10.51) and severe anemia (HR = 15.53, 95%CI:11.56–20.92) among PLWH with CD4 cell counts < 100 cells/mm3 than have been previously reported." (PMID 32197585, 2020).
anemia (continued). "Our study has shown that ART use in HIV infected pregnant women with anaemia improves haemoglobin concentration regardless of baseline CD4 count or WHO stage of HIV disease within the first 7 months of ART usage." (PMID 33425126, 2020). "Time to the post-enrolment gain of 100 CD4 cells/L was 43% slower for individuals that began the study with macrocytic anemia vs. no anemia." (PMID 30935133, 2019). "Overall, the accuracy of the Presto machine must be considered, since over-estimation of CD4 count could result in missing cases of advanced HIV disease, and overestimation of Hgb concentration could result in missed cases of anemia." (PMID 30794637, 2019). "At the baseline, CD4 cell counts were similar for adult PLWHA with microcytic or ACD compared to those without anemia." (PMID 30935133, 2019). "At month 18, there was no anemia-type related differences in CD4, BMI, QOL and frailty-related phenotype." (PMID 30935133, 2019). "In addition, lower CD4 means the progression of HIV disease with higher viral burden, which increased cytokine-mediated myelosuppression leading to anaemia." (PMID 30816082, 2019). "On the other hand, adult PLWHA with macrocytic vs. no anemia at enrollment started had a higher baseline CD4 cell count (difference: 43.0, 95% CI: 13.4, 72.1)." (PMID 30935133, 2019). "However, from these variables, Educational status, years lived with a virus, CD4 count, infection with intestinal parasites, HAART status and BMI <18.5% were predictors of anemia." (PMID 31596865, 2019). "Over 18-month of follow-up, the relationships between CD4 counts did not significantly vary by anemia (data not shown, p-value for anemia × time = 0.56) or its severity (p-value for anemia severity × time interaction = 0.11) at baseline." (PMID 29649107, 2018). "PLWHA with sustained moderate/severe or progressive anemia had a substantial deficit in CD4 cell counts compared to PLWHA without anemia (difference = −73 cells/uL, 95% CI: −126 to −20 cells/uL)." (PMID 29649107, 2018). "Ongoing HIV replication and anemia were strong predictors for OI development independent of the CD4 cell count." (PMID 30383836, 2018). "This study was designed to characterize iron homeostasis and inflammation in relation to anemia at HIV diagnosis, and after the decline of virus titers in plasma due to cART introduction in a group of HIV-infected patients with mild anemia and CD4+ cells > 200/mm3." (PMID 29258550, 2017). "World Health Organization disease stage, CD4 count, age, and year of ART initiation were highly predictive of mortality, while anemia at baseline was not statistically significantly associated." (PMID 26198439, 2015). "Even though distribution of anemia status was higher in females with lower CD4 +T cell counts in HAART naïve groups, it was not statistically significant regardless of HAART in relation to gender." (PMID 25658626, 2015). "The final Cox proportional hazard model fitted identified CD4 count <50/ug, weight <40 kg, lower educational status (no or primary education) and anaemia at base line and male gender were found to be the predictors of mortality." (PMID 24498093, 2014). "A significantly larger proportion of the 262 pregnant women with anaemia (56/262) were in an advanced stage of HIV disease (CD4<200) when compared to women without anaemia (10/146) (21.4% vs 6.9%; p<0.001)." (PMID 25222119, 2014). "The observed higher percentage of CD3+, CD4+, and CD19+ cells with TLR7 among subjects with anemia may reflect the presence of chronic inflammation and increased proinflammatory cytokines." (PMID 24692849, 2014). "Among patients with anaemia, there was a higher percentage of TLR7-positive CD3+ (4.19% ± 5.45), CD4+ (4.19% ± 5.45), and CD19+ cells (5.87% ± 8.71), compared to patients with haemoglobin concentration >12 g/dL (0.55% ± 1.08, P < 0.05; 0.55% ± 1.08, P < 0.03; 0.85% ± 2.24, P < 0.02, resp)." (PMID 24692849, 2014).
anemia (continued). "Anaemia remains the prognostic marker of future progression or death, independent of CD4+ count and viral load among HIV individuals." (PMID 24729787, 2014). "CD4 cell count and HIV viral load (either baseline or time-updated) were not independently associated with anaemia after 12 months of ART." (PMID 25528467, 2014). "The median CD4 count among women with anaemia and without anaemia was 320 (IQR 217–463) and 392 (IQR 285–546) respectively." (PMID 25222119, 2014). "The prevalence ratio of having anemia decreased with increasing CD4 count and increasing BMI although the difference by CD4 category was not statistically significant." (PMID 25209550, 2014). "Although, HIV patients with CD4 cell count <200 cells/μl had higher prevalence of anemia (18%) after HAART initiation, there was no significance association between anemia and CD4 cell count (P =0.051)." (PMID 25335859, 2014). "Anaemia was more severe in patients who were younger, female, had lower CD4 cell counts, higher HIV viral loads and had no medical history of TB." (PMID 25528467, 2014). "The prevalence of anemia was considerably higher compared to a rural Ugandan cohort which found 18.9% anemic HIV-positive individuals even though lower hemoglobin cut-offs were used in the rural cohort and the CD4 cell counts were comparable in both cohorts." (PMID 25209550, 2014). "When testing small volume (2.0 ml) urine samples, the diagnostic sensitivity was not only greater among those with lower CD4 counts as previously reported, but was also higher among those with higher CRP concentrations, severe anemia and in those who later died." (PMID 24168211, 2013). "In this study, as the immunity of a patient decreases, anaemia was more prevalent in patients rather than in HIV positive patients who have relatively high CD4 count." (PMID 24238076, 2013). "Serum ferritin concentrations were elevated, especially in patients with anemia (p = 0.07) and/or low CD4 counts (p < 0.001), and were not related to hsCRP or HCV infection." (PMID 21827653, 2011). "A similar lack of response to T cell suppression has been observed in cattle where depletion of CD4 or CD8 T cells in both susceptible and trypanotolerant breeds did not influence the severity of anaemia after T. congolense infection." (PMID 19365556, 2009). "Men presented at an older age and with more advanced disease (lower CD4 counts, lower BMI, anemia and WHO III and IV disease) compared to non-pregnant women, and non-pregnant women presented with more advanced disease compared to pregnant women." (PMID 20017918, 2009). "Of note, CD4+ T cells sustain CD8+ T cell function during chronic LCMV infection and could be involved in this anemia, yet determination of an independent role for CD4+ T cells would be difficult since CD4+ depletion profoundly affects the responses of all T cell subsets in this model system." (PMID 39820014, 2025). "Importantly, a decrease of CD4 T-cell counts was detected according to anemia severity (without anemia: 110 cells/μL; mild: 69 cells/μL [23.8-140]; moderate: 57 cells/μL [25.5-120]; severe: 42 cells/μL; p<0.001)." (PMID 37143662, 2023). "In line with our results, a recent study showed that anemia status influences the blood transcriptome with enrichment of erythrocyte differentiation genes as well as ARG1 in anemic children, but decreased signatures of CD4+ T cell activation and differentiation." (PMID 34893694, 2021). "Besides, in multivariable models, WHO clinical staging III and IV, CD4 count below the threshold level, CPT non-users, and poor level of adherence were associated with the time to detection of anemia." (PMID 33785009, 2021). "Anemia status was taken as a dependent variable and sex, residence, educational status, baseline WHO clinical stage, social drug use, OPI, ART regimen combination, age category, baseline BMI, baseline CD4 count, and duration of AZT treatment were taken as independent or intercept model." (PMID 34583644, 2021).
anemia (continued). "First, the proportion of adults with HAART experience was similar across anemia-types at enrolment, suggesting that macrocytosis-related higher CD4 at enrolment may not be entirely explained by variations in HAART experience." (PMID 30935133, 2019). "In the severe outcome case-control population, cases and controls differed significantly by the following baseline characteristics: country (p = 0.01), BMI (p = 0.003), prior TB (p = 0.02), CD4 count, hypoalbuminemia, and anemia (all p < 0.001) (data not shown)." (PMID 30244671, 2018). "In the incident active TB case-control population, cases and controls differed significantly by the following baseline characteristics: BMI (p = 0.001), prior TB (p = 0.02), CD4 count (p = 0.02), country, hypoalbuminemia, and anemia (all p < 0.001) (data not shown)." (PMID 30244671, 2018). "Anemia is associated with progression to AIDS, shorter survival times,and it is a predictor of poorer prognosis for HIV infected patients independent of the CD4 count." (PMID 29632668, 2018). "However missing CD4 data and being anaemic at the time of switch were important predictors of drug substitution among patients initiated on AZT/ABC + 3TC + LPVr, indicating exacerbated or unresolved anaemia." (PMID 28364563, 2016). "Remained in the model, by significantly increasing the risk of TB: indication for but non-implementation of treatment for LTBI and TST not tested; baseline CD4 cell count <200 cell/mm3; anemia (and not testing for it); previous treatment for TB; BMI <18.5 kg/m2 and being illiterate." (PMID 23675515, 2013). "Lower D4T use in men and at higher CD4 count levels may be explained by the lower prevalence of anaemia in men and in healthier patients, and hence the absence of a contraindication to zidovudine (AZT) use." (PMID 21955541, 2011). "There was a strong negative correlation between anemia and CD4 counts in this study." (PMID 19678930, 2009). "Moreover, anemia induction by virus-specific CD4+ T cells was efficiently suppressed by virus-nonspecific Treg cells." (PMID 19006695, 2008). "Comparison of the results of short-term treatment showed that those patients with a CD4 cell count of 200–350 cells/mm3 at diagnosis and initial treatment showed the highest success rate of 63.1%, followed by patients with a VL of < 55,000 copies/mL and no anemia at baseline (59.9%)." (PMID 37016006, 2023). "Moreover, WHO clinical staging of III/IV [AHR: 4.2, 95% CI: 1.80, 11.1], low CD4 count below threshold [AHR: 1.9, 95% CI: 1.09, 3.37], cotrimoxazole preventive therapy non-users, and poor level of adherence [(AHR: 2.4, 95% CI: 1.20, 4.85] were the main predictors of the time to detection of anemia." (PMID 33785009, 2021). "However, this initial macrocytic anemia related CD4 advantage in comparison with no anemia is absent in all follow-up intervals whether macrocytic anemia is defined at baseline or per value at current follow-up interval." (PMID 30935133, 2019). "The investigations included a full blood count with microcytic normochromic anemia and negative syphilis serology (TPHA), while the CD4 count was 365 cells/mm3, and the viral load was 215 copies/mL." (PMID 40385314, 2025). "On the same HIV viral load and CD4+ T-cell count, HIV/AIDS-infected patients with comorbid anemia die at a much higher rate than those without anemia, with decreased mortality after correction of anemia." (PMID 39006953, 2024). "Having a CD4 cell count below the threshold, ever exhibiting only fair or poor adherence to ART, co-morbidity of anemia, ever taking TPT, and not having initiated ART within 7 days were significant predictors of an increased incidence of OIs among this group." (PMID 37205221, 2023). "Infection of nu/nu mice, lacking both CD4 and CD8 T cells, resulted in a diminished anemia phenotype compared to C57BL/6 mice, and coincided with reduced levels of IFNγ in serum and spleen cell culture." (PMID 26070118, 2015).